KLK6 (kallikrein related peptidase 6)
Diseases named in the same sentence as KLK6 in open-access papers (continued):
Sharing a sentence is not in itself a finding about the gene and the disease.
colorectal tumors (3 papers, 2021 to 2024). "The keratins altered in KLK6-high colorectal tumors may be further evaluated as biomarkers in the CRC progression." (PMID 34065672, 2021).
esophageal cancer (3 papers, 2013 to 2024). A primary or metastatic malignant neoplasm involving the esophagus. "In each of the following cancers, only one KLK was significantly upregulated: hepatocellular carcinoma (KLK4: 2-fold), stomach adenocarcinoma (KLK6: 11-fold) and esophageal carcinoma (KLK4: 3-fold)." (PMID 29707153, 2018). "The positively correlated genes (SLUT2B1, PPL, KLK6, CRYBG2, SCEL, ADGRF4 and KLK8) were more frequently expressed in esophageal cancer than normal tissue (p < .05)." (PMID 38241178, 2024). "In our study KLK6 was increased in esophageal carcinoma, but could not achieve statistical significance." (PMID 29707153, 2018).
experimental autoimmune encephalomyelitis (3 papers, 2011 to 2025). An autoimmune demyelinating disease of the central nervous system that is produced experimentally in animals by the injection of homogenized brain or spinal cord in Freund's adjuvant. "In addition, increased KLK6 was observed in experimental autoimmune encephalomyelitis/MS and determined to represent a pathogenic mediator of inflammatory demyelination." (PMID 41255373, 2025). "Additionally, blocking KLK6 activity diminishes clinical and histological disease as well as Th1 inflammatory responses in experimental autoimmune encephalomyelitis (EAE), yet the role and mechanism of action of KLK6 in immune function has not been previously examined." (PMID 21464892, 2011).
lung adenocarcinoma (3 papers, 2018 to 2025). A carcinoma that arises from the lung and is characterized by the presence of malignant glandular epithelial cells. "Lung adenocarcinoma and lung squamous cell carcinoma showed significant up-regulation of 3 KLKs: KLK6 (7-fold and 19-fold), KLK8 (3-fold and 15-fold) and KLK12 (2-fold and 3-fold) and significant down-regulation of KLK11 (6-fold and 5-fold)." (PMID 29707153, 2018). "Additionally, there is evidence presenting that kallikrein-related peptidase 6 (KLK6) and trypsin, two members of the serine protease family, can activate protease-activated receptor-2 (PAR2) to boost the growth of lung adenocarcinoma (LUAD) cells, thus to advance cancer progression." (PMID 33968158, 2021).
non-small cell lung carcinoma (3 papers, 2013 to 2024). A group of at least three distinct histological types of lung cancer, including non-small cell squamous cell carcinoma, adenocarcinoma, and large cell carcinoma. "In non-small cell lung cancer, high expression of KLK6 was an indicator of tumor proliferation and poor prognosis; KLK6 was possible to be a potential novel diagnostic biomarker for LUSC." (PMID 38363409, 2024). "KLK6 regulated the proliferation and apoptosis of non-small-cell lung cancer cells via cleavage and activation of PAR2, which in turn activated the ligand-dependent epidermal growth factor receptor (EGFR) pathway." (PMID 34439122, 2021).
vascular dementia (3 papers, 2020 to 2022). A degenerative vascular disorder affecting the brain. "The 3xTg-AD model showed an accentuated upregulation of Klk6 and Lcn2, which have been evaluated as possible markers of AD and vascular dementia, respectively." (PMID 34702310, 2021).
Ascites (2 papers, 2011 to 2022). Accumulation of fluid in the peritoneal cavity (between the layers of the peritoneum that lines the abdomen). "As such, groups KLK5/10 and KLK6/10 had a marked reduction in the incidence of ascites and a corresponding longer survival." (PMID 22102857, 2011). "Ascitic fluid analysis is essential for the diagnosis of malignant ascites, and one would speculate that KLK6 expression may have an important value for distinguishing between ascites from malignant colon cancer and ascites, which may develop from benign diseases." (PMID 35883559, 2022).
astrocytoma (2 papers, 2004 to 2015). "Prior studies demonstrate that higher levels of KLK6 immunoreactivity in grade IV astrocytoma are associated with poor patient survival." (PMID 26231762, 2015). "Like KLK6, higher levels of KLK1, KLK7, KLK8, KLK9 and KLK10 were all found to be associated with higher astrocytoma grade." (PMID 26231762, 2015). "Together these studies support the concept that KLK6 mediates its effects in astrocytoma cells in a PAR1-dependent fashion and that this is likely to involve both cell survival and invasion." (PMID 26231762, 2015). "Through a comprehensive parallel analysis of immunoreactivity for six kallikreins in grade III and IV astrocytoma we determined that tumor core staining for KLK7 and KLK9, like KLK6, has significant prognostic value with regard to patient survival." (PMID 26231762, 2015). "Expression of KLK1, KLK6, KLK7, KLK8, KLK9 and KLK10 protein was assessed by immunohistochemical analysis of grade III (n = 8) and grade IV (n = 60, n = 55 for KLK1) astrocytoma samples." (PMID 26231762, 2015). "In this study we determined KLK1, KLK6, KLK7, KLK8, KLK9 and KLK10 protein expression in two independent tissue microarrays containing 60 grade IV and 8 grade III astrocytoma samples." (PMID 26231762, 2015).
bladder cancer (2 papers, 2020 to 2022). "Our findings also revealed that inhibition of KLK6 restrained the malignant phenotypes of bladder cancer cells." (PMID 36193495, 2022).
breast cyst (2 papers, 2004 to 2021). A fluid-filled closed cavity or sac that is lined by an EPITHELIUM and found in the BREAST. "Using the ELISA test, antigens against KLK6 were found in breast cyst fluid, male and female serum and milk." (PMID 34858488, 2021).
colon adenoma (2 papers, 2021 to 2024). An adenoma that arises from the colon. "The fact that KLK6 is associated with a more aggressive tumor phenotype and is detectable in colon adenomas offers a potentially valuable clinical tool in differentiating the more aggressive CRC tumors." (PMID 39594797, 2024). "Our findings imply that KLK6 overexpression accelerates Apc-mutant tumorigenesis and can be utilized for the early detection of colon adenomas." (PMID 39594797, 2024). "In the small intestinal and colon adenomas of ApcMin/+ mice, Klk6 transcript levels were nearly four-fold higher than in adjacent microscopically normal tissue (p < 0.03)." (PMID 39594797, 2024). "We found that kallikrein 6 (KLK6), a secreted serine protease, is overexpressed in the intestinal tract of Apc-mutant multiple intestinal neoplasia (ApcMin/+) mice and can be detected in mouse colon adenomas using imaging techniques with fluorescence-labeled KLK6 antibody." (PMID 39594797, 2024).
colorectal adenocarcinoma (2 papers, 2022). The most common type of colorectal carcinoma. "Previous studies have reported that KLK6 mRNA has a clinical utility and a prognostic value, as a biomarker in colorectal adenocarcinoma since its expression in CRC correlated significantly with tumor stage and tumor grade and advanced Dukes’ stage, liver metastasis, and poor prognosis." (PMID 35883559, 2022). "Our findings are in agreement with another report that found that KLK6 mRNA expression is an independent, unfavorable molecular prognostic biomarker in colorectal adenocarcinoma, with an additional prognostic value in patients without regional or distant metastases." (PMID 35883559, 2022).
cutaneous melanoma (2 papers, 2011 to 2017). A primary melanoma arising from atypical melanocytes in the skin. "Interestingly, changes in the KLK6 and KLK7 expression profile were associated with the transition from thin to thick cutaneous melanomas, being also significantly correlated to other genes functionally related to keratinocyte differentiation, cell shedding, invasion, and migration." (PMID 22032772, 2011).
glioma (2 papers, 2015 to 2019). A benign or malignant brain and spinal cord tumor that arises from glial cells (astrocytes, oligodendrocytes, ependymal cells). "Providing the rationale for the current study, we recently demonstrated that elevated levels of KLK6 are associated with high-grade glioma and poor patient survival." (PMID 26231762, 2015). "Our prior studies suggest that KLK6 directly promotes glioma cell survival, including resistance to radiation and temozolomide, in a PAR1-dependent manner." (PMID 26231762, 2015). "The potential pathophysiological significance of KLK6 to glioma appears to extend to lower grade tumors as well, since patients with mixed intracranial tumors positive for KLK6 expression also have unfavorable prognoses compared to those lacking expression." (PMID 26231762, 2015). "Interestingly, the KLK6-mediated activation of PAR1 was shown to play an essential role in its ability to promote glioma cell survival." (PMID 26231762, 2015). "The kallikreins KLK6, KLK7, and KLK9 have been shown to have higher protein levels in Grade IV glioma compared to Grade III tumours and consequently may have utility as prognostic markers for patient survival." (PMID 32082376, 2019).
laryngeal carcinoma (2 papers, 2014 to 2026). Carcinoma that arises from the laryngeal epithelium. "The diagnostic potential of KLK6 was then validated in circulating plasma samples from laryngeal cancer patients, benign patients, and healthy individuals." (PMID 24669031, 2014). "SPINK5 knockdown enhanced the activity of KLK6 and the activation of the PI3K/AKT/mTOR signaling pathway in laryngeal cancer cells." (PMID 42062847, 2026).
leukemia (2 papers, 2015 to 2016). A malignant (clonal) hematologic disorder, involving hematopoietic stem cells and characterized by the presence of primitive or atypical myeloid or lymphoid cells in the bone marrow and the blood. "Notably, KLK6 also promotes survival of the Jurkat leukemia T cell line in a PAR1 dependent fashion." (PMID 26231762, 2015).
Lewy body disease (2 papers, 2014 to 2018). "Phosphorylated forms of α-syn which are more abundant in Lewy body diseases, and mutant forms of α-syn that accumulate in familial forms of PD, are resistant to proteolytic cleavage by KLK6." (PMID 25476568, 2014). "Together, these data provide a strong case for a regulatory role for KLK6 and suggest that reduced KLK6-mediated cleavage of α-syn and α-syn-P129 contribute to the pathogenesis of Lewy body diseases." (PMID 25476568, 2014).
liver disease (2 papers, 2021 to 2022). "For the investigation of KLK6 and MEP1A tissue expression, liver biopsy sections from five HCC, four benign liver disease including cirrhosis and five cases with normal liver tissue without disease were selected from the Arden tissue bank." (PMID 34359689, 2021). "In contrast, we could not detect any KLK6 in ascitic fluids from non-malignant liver diseases such as cirrosis, liver hepatic insufficiency, or post-surgery inflammation." (PMID 35883559, 2022).
metastasis (2 papers, 2017 to 2022). The spread or migration of cancer cells from one part of the body (where they first appeared) to another. "Importantly, high levels of KLK6 protein were detected in the ascites of CRC patients with peritoneal metastasis, but not in benign ascites." (PMID 35883559, 2022).
Netherton syndrome (2 papers, 2022 to 2024). Netherton syndrome (NS) is a skin disorder characterized by congenital ichthyosiform erythroderma (CIE), a distinctive hair shaft defect (trichorrhexis invaginata; TI) and atopic manifestations. "LEKTI can diminish the activities of epidermal serine proteases such as KLK5, KLK6, KLK7, KLK13, and KLK14 in skin, and a mutation in the SPINK5 gene is characteristic of Netherton syndrome, which presents with serious dehydration, itching, and chronic skin inflammation." (PMID 35955819, 2022).
neuroblastoma (2 papers, 2012 to 2014). Neuroblastoma (NB) is the most common solid, extracranial childhood tumor. "To assess the functional relevance of down-regulation of KLK6 level and CAPN1, we used SH-SY5Y neuroblastoma cells, within which there was partial co-localisation of KLK6 and CAPN1 with α-syn." (PMID 25476568, 2014). "We have shown that KLK6 is partly co-localised with α-syn in SH-SY5Y neuroblastoma cells, in a distinctive subplasmalemmal distribution, and confirmed that down-regulation of KLK6 results in increased endogenous α-syn." (PMID 25476568, 2014).
oligodendroglioma (2 papers, 2015 to 2018). A well-differentiated (WHO grade II), diffusely infiltrating neuroglial tumor, typically located in the cerebral hemispheres. "Many of these candidates (e.g. ELTD1, SDHB, SEPW1, SLC17A7, SZRD1, THAP3, ZBTB17) are likely to push, whereas others (e.g. CAP1, HBXIP, KLK6, PARK7, PTAFR) might counteract oligodendroglioma development." (PMID 29890994, 2018). "Interestingly, several of these genes (e.g. ELTD1, SDHB, SEPW1, SLC17A7, SZRD1, THAP3, ZBTB17) are likely to push, whereas other genes (e.g. CAP1, HBXIP, KLK6, PARK7, PTAFR) might restrict oligodendroglioma development." (PMID 29890994, 2018).
oral squamous cell carcinoma (2 papers, 2021). "A previous study reported that decreased expression of KLK6 in oral squamous cell carcinoma (OSCC) stimulated EMT, leading to enhanced migration and invasion in vitro." (PMID 34552064, 2021).
Psoriasiform dermatitis (2 papers, 2021 to 2022). A skin abnormality characterized by redness and irritation, with thick, red skin that displays flaky, silver-white patches (scales). "High KLK6 expression levels were linked to inflammatory skin diseases, such as severe psoriasiform dermatitis." (PMID 34439122, 2021). "Keratinocyte-specific gene modifications have induced psoriasiform dermatitis—for instance, in K5.Stat3c transgenic mice, Klk6 transgenic mice, and K14-Rac1V12−/+ mice." (PMID 35457132, 2022).
psoriatic arthritis (2 papers, 2014 to 2021). Joint inflammation associated with psoriasis. "Moreover, overexpression of KLK6+ caused increased expression of genes and proteins associated with psoriatic arthritis as well as pathological changes to the joint such as bone damage, synovitis, and impaired mobility." (PMID 34502257, 2021). "A transgenic mouse model that overexpresses kallikrein-related peptidase-6 (KLK6+) in keratinocytes, psoriatic arthritis markers such as IL-17A, IL-23 and IL-6 were all elevated." (PMID 34502257, 2021).
skin atrophy (2 papers, 2016 to 2021). The degeneration and thinning of the epidermis and dermis. "The goals of the current study were to assess the expression of KLK6 at mRNA/protein levels during glucocorticoid-induced skin atrophy and to determine its role in the development of resistance to the glucocorticoids using KLK6 knockout (KO) mice." (PMID 27283773, 2016). "As we showed here, KLK6 plays an important role in skin protection against glucocorticoid-induced skin atrophy." (PMID 27283773, 2016). "Also, KLK6 is also induced upon chronic GC treatment likely as a mechanism aimed to regenerate the epidermis after GC-induced skin atrophy; in agreement with this, Klk6 KO mice showed decreased steroid tachyphylaxis." (PMID 34576214, 2021). "All previously published data suggested that KLK6 can counteract the anti-proliferative pressure of glucocorticoids and may play an important role in epidermal regeneration after steroid-induced skin atrophy." (PMID 27283773, 2016). "Thus, the lack of KLK6 did not affect the induction of skin atrophy by chronic topical glucocorticoid." (PMID 27283773, 2016).
subarachnoid hemorrhage (2 papers, 2012 to 2022). A serious neurological disorder characterized by intracranial hemorrhage into the subarachnoid space. "Serum concentrations of KLK6 and S100B (ng/mL) in the initial sample and all samples collected within the first 56 hours from patients with subarachnoid hemorrhage." (PMID 23049835, 2012).
adenoma (1 paper, 2024). A neoplasm arising from the epithelium. "Thus, KLK6 overexpression in the colorectal tissue could be contributing to the formation of high-risk lesions in the adenoma-carcinoma sequence and can indicate early-stage carcinoma development." (PMID 39594797, 2024). "The adenoma tissue was stained strongly for KLK6 in the cytoplasm and luminal surface areas, and the less intense staining for KLK6 is seen in the adjacent microscopically normal tissue." (PMID 39594797, 2024). "A first analysis of KLK6 expression in the intestinal tract of Apc-mutant multiple intestinal neoplasia (ApcMin/+) mice revealed up to four-fold induction of Klk6 mRNA levels in adenomas relative to its level in the adjacent mucosa." (PMID 39594797, 2024). "The analysis revealed the difference between CPC;Apcfl/fl;Klk6+/+ mice and mice heterozygous or homozygous for the Klk6 gene in adenoma size distribution." (PMID 39594797, 2024). "A strong KLK6-specific fluorescence signal was detected in the adenoma regions of the ApcMin/+ mice, while the control mice showed no appreciable fluorescence in any of the tissues imaged.The presence of KLK6 protein in adenomas was also confirmed by immunohistochemistry on resected colons." (PMID 39594797, 2024). "Interestingly, the Klk6 disruption significantly decreased the percentage of adenomas larger than 2 mm (p ≤ 0.0018)." (PMID 39594797, 2024). "In this study, we found that Klk6 gene expression was significantly elevated (up to four-fold higher compared to the microscopically normal tissue) in the adenomas formed in the intestinal tract of the ApcMin/+ mouse model of the human familial adenomatous polyposis disease." (PMID 39594797, 2024). "The overexpression of KLK6 has been reported in the adenomas of CRC patients." (PMID 39594797, 2024). "This experiment suggests that KLK6 may be utilized as a potential marker of adenomas." (PMID 39594797, 2024). "Specifically, the higher percentage of adenomas with sizes 2.0–3.0 mm and above 3.0 mm was seen in CPC;Apcfl/fl;Klk6+/+ mice compared to the CPC;Apcfl/fl;Klk6+/fl and CPC;Apcfl/fl;Klk6fl/fl mice (p = 0.0018 and p = 0.0001, respectively)." (PMID 39594797, 2024). "The disruption of KLK6 enzyme function in CPC;Apcfl/fl;Klk6fl/fl mice resulted in the overall two-fold suppression of adenoma formation compared to the CPC;Apcfl/fl;Klk6+/+ mice (p = 0.01)." (PMID 39594797, 2024). "At the same time, the two-fold increase in the percentage of adenomas less than 2 mm was observed in the mice of CPC;Apcfl/fl;Klk6+/fl and CPC;Apcfl/fl;Klk6fl/fl genotypes (31.25% and 35.96%, respectively) compared to CPC;Apcfl/fl;Klk6+/+ mice (18.68%)." (PMID 39594797, 2024). "Overall, the total number of adenomas per mouse was significantly higher in the CPC;Apcfl/fl;Klk6+/+ mice (15.5 ± 4.22) and CPC;Apcfl/fl;Klk6+/fl mice (15.00 ± 5.47) than in the CPC;Apcfl/fl;Klk6fl/fl mice (8.83 ± 4.78) (p = 0.005)." (PMID 39594797, 2024). "In contrast, the number of high-grade adenomas in the small intestine of CPC;Apcfl/fl;Klk6fl/fl mice (0.58 ± 0.80) was significantly lower than in CPC;Apcfl/fl;Klk6+/+ mice (1.7 ± 0.95) and CPC;Apcfl/fl;Klk6+/fl mice (1.71 ± 1.38) (p = 0.03 and p = 0.04, respectively)." (PMID 39594797, 2024). "Furthermore, the number of high-grade adenomas formed in the small intestine was significantly lower in the CPC;Apcfl/fl;Klk6fl/fl mice as compared to the Klk6-expressing CPC;Apcfl/fl;Klk6+/+ mice (p = 0.03)." (PMID 39594797, 2024). "We found that CPC;Apcfl/fl mice with disrupted Klk6 gene expression (CPC;Apcfl/fl;Klk6fl/fl) had a significantly smaller average size of the small intestinal and colon crypts (p < 0.001 and p = 0.04, respectively) and developed a significantly fewer adenomas (p = 0.01)." (PMID 39594797, 2024).
amyloid (1 paper, 2019). "Its location at the neurovascular unit and close to the amyloid clearing perivascular spaces makes KLK6 a suspect to be involved in the amyloid clearance process or immunological processes that impair amyloid clearance via perivascular drainage." (PMID 31467673, 2019).